G6PD (glucose-6-phosphate dehydrogenase)
Diseases named in the same sentence as G6PD in open-access papers (continued):
Sharing a sentence is not in itself a finding about the gene and the disease.
endothelial dysfunction (6 papers, 2016 to 2023). In vascular diseases, endothelial dysfunction is a systemic pathological state of the endothelium (the inner lining of blood vessels) and can be broadly defined as an imbalance between vasodilating and vasoconstricting substances produced by (or acting on) the endothelium. "We hypothesized that an increase in G6PD activity in vivo could prevent an age-associated increase in the levels of arginase in aorta and ameliorate endothelial dysfunction." (PMID 36835034, 2023). "The main finding of the present work is that an overexpression of the enzyme G6PD modulates arginase in the aorta from old mice, reversing the endothelial dysfunction observed with aging." (PMID 36835034, 2023). "The effects of CoCl2 and the involvement of G6PD in endothelial dysfunction have been confirmed in primary human aortic endothelial cells." (PMID 35666067, 2022). "Our data identified G6PD as a novel target for CoCl2‐induced endothelial dysfunction." (PMID 35666067, 2022). "Furthermore, this study demonstrated the protective effect of NAC against CoCl2‐induced endothelial dysfunction by enhancing G6PD activity, supporting its therapeutic potential." (PMID 35666067, 2022). "Furthermore, pretreatment with NAC could ameliorate CoCl2‐induced endothelial cell damage by activating G6PD activity, indicating its therapeutic potential in treating hypoxia‐related endothelial dysfunction." (PMID 35666067, 2022). "Thus, inhibition of G6PD in vascular cells abrogated not only the over-activation of NADPH oxidase but also the subsequent exacerbated inflammation and endothelial dysfunction, which may help to explain a number of other experimental and clinical observations." (PMID 27245224, 2016).
head and neck cancer (6 papers, 2017 to 2025). A primary or metastatic malignant neoplasm affecting the head and neck. "C-myc-directed NRF2 drives the malignant progression of head and neck cancer through the activation of glucose-6-phosphate dehydrogenase and transketolase." (PMID 35770119, 2022). "For example, G6PD in head and neck cancer cell lines SCC-6 and SCC1483 was modulated by radiation doses compared to untreated." (PMID 28262749, 2017). "However, only one prior study revealed that G6PD was modulated by FOXM1 for participating radio-resistance in head and neck cancer." (PMID 33859744, 2021). "Furthermore, G6PD- and TKT-regulated nucleotide biosynthesis is more important than redox regulation for maintaining the malignant features of head and neck cancer." (PMID 33859744, 2021). "Taken together, these data support the potential for use of the NRF2/G6PD/TKT gene signature as a prognostic biomarker and for the development of NRF2-targeted therapies that alter cellular metabolism as novel and promising treatment options for head and neck cancer." (PMID 33859744, 2021).
hepatitis B virus infection (6 papers, 2015 to 2024). A viral infection caused by the hepatitis B virus. "Given the global distribution of hepatitis B, its association with poor treatment response, and the increased risk of HCC development, we specifically investigated the functional role of miR-122 in regulating G6PD in chronic hepatitis B (CHB) patients." (PMID 37627157, 2023).
hereditary elliptocytosis (6 papers, 2013 to 2025). Hereditary elliptocytosis (HE) is a rare clinically and genetically heterogeneous disorder of the red cell membrane characterized by manifestations ranging from mild to severe transfusion-dependent hemolytic anemia but with the majority of patients being asymptomatic. "Management of G6PD and hereditary elliptocytosis remains supportive, focusing on transfusions when required, folic acid supplementation, and monitoring for iron overload." (PMID 41458859, 2025).
myocardial infarction (6 papers, 2016 to 2026). Gross necrosis of the myocardium, as a result of interruption of the blood supply to the area, as in coronary thrombosis. "Mice deficient in glucose 6-phosphate dehydrogenase are susceptible to cardiovascular disease and ventricular dilation in response to myocardial infarction or pressure overload-induced heart failure." (PMID 36312243, 2022). "Intramyocardial delivery of modRNA encoding PKM2 or glucose-6-phosphate dehydrogenase (G6PD) enhances glycolysis and PPP activity, stimulates mononuclear CM proliferation, and improves cardiac function after myocardial infarction." (PMID 41015973, 2025). "Other contraindications include hypersensitivity reactions, retinopathy, porphyria, epilepsy, pre-existing maculopathy, glucose-6-phosphate dehydrogenase (G6PD) deficiency, recent myocardial infarction (MI), and QTc of >500 msec." (PMID 32953365, 2020).
paroxysmal nocturnal hemoglobinuria (6 papers, 2015 to 2025). Paroxysmal nocturnal hemoglobinuria (PNH) is an acquired clonal hematopoietic stem cell disorder characterized by corpuscular hemolytic anemia, bone marrow failure and frequent thrombotic events. "Results of the Coomb’s test, paroxysmal nocturnal hemoglobinuria (PNH) test, G6PD enzyme activity test, osmotic fragility test and Hb electrophoresis test were all within normal limits." (PMID 37697358, 2023).
vitiligo (6 papers, 2014 to 2025). Generalized well circumscribed patches of leukoderma that are generally distributed over symmetric body locations and is due to autoimmune destruction of melanocytes. "A previous study has revealed that G6PD activity and polymorphism is associated with insufficient melanocyte activity and oxidative stress response in vitiligo in the Gujarat population." (PMID 39092715, 2024). "A study in the Gujarat population showed a genetic and biochemical association of the G6PD 3’UTR rs1050757 polymorphism with vitiligo." (PMID 36439174, 2022). "Next, since SIRT7 is a desuccinylase, we presented evidence that the SIRT7‐mediated desuccinylation of G6PD contributed to the progression of vitiligo." (PMID 39092715, 2024). "Here, we found that SIRT7 was highly expressed in vitiligo skin lesions, and SIRT7 promoted pigmentation of melanocytes by mediating desuccinylation of G6PD, indicating a new approach for the treatment of vitiligo." (PMID 39092715, 2024). "In summary, our findings suggest that SIRT7 suppresses pigmentation of melanocytes in vitiligo progress by facilitating desuccinylation of G6PD, contributing to the targeted therapies for vitiligo." (PMID 39092715, 2024). "Glucose-6-phosphate dehydrogenase levels have been repeatedly reported to be decreased in vitiligo." (PMID 38715599, 2024). "Growing evidence has emphasized that G6PD is involved in the pathogenesis of vitiligo." (PMID 39092715, 2024). "G6PD activity and levels are lower in patients with vitiligo than that in the control." (PMID 39092715, 2024). "Glucose 6‐phosphate dehydrogenase (G6PD) is an oxidative stress defense regulator during vitiligo." (PMID 39092715, 2024). "Silencing of SIRT7 promotes pigmentation of melanocytes by succinylating G6PD, suggesting that SIRT7‐mediated G6PD desuccinylation may promote vitiligo progression." (PMID 39092715, 2024). "The results suggest that SIRT7 promotes the progression of vitiligo by desuccinylating G6PD." (PMID 39092715, 2024). "Furthermore, melanocytes in vitiligo patients are more sensitive to G6PD inhibition than normal melanocytes." (PMID 36439174, 2022). "Therefore, the progression of vitiligo may be due to oxidative damage mediated by impaired G6PD levels." (PMID 39092715, 2024). "Therefore, abnormal glucose metabolism in vitiligo patients may result from an imbalance in the secretion of pro-inflammatory factors, low oxidative stress, or impaired G6PD levels." (PMID 36439174, 2022). "To explore the modification of SIRT7 on G6PD in vitiligo, we found that silencing of SIRT7 elevated the protein and succinylation levels of G6PD in PIG3V cells, assessing by Western blot analysis." (PMID 39092715, 2024). "Low levels of catalase (CAT), glutathione peroxidase (GPx), glucose-6-phosphate dehydrogenase (G6PD), and superoxide dismutase (SOD) have been demonstrated in the epidermis and blood of vitiligo patients." (PMID 36439174, 2022). "A possible explanation for this phenomenon resides in the low levels of antioxidants, including catalase (CAT), glutathione peroxidase (GPx), glucose-6-phosphate dehydrogenase (G6PD) and superoxide dismutase (SOD), in skin lesions and serum of patients with vitiligo." (PMID 40303919, 2025).
Allergy (5 papers, 2007 to 2024). An allergy is an immune response or reaction to substances that are usually not harmful. "Prophylaxis for patients with sulfa allergies is even less certain; the recommendation is to consider dapsone/pyrimethamine/leucovorin in these patients if glucose-6-phosphate dehydrogenase (G6PD) is negative, but this regimen is riddled with adverse effects and adds a significant pill burden." (PMID 39473451, 2024).
Alzheimer disease (5 papers, 2017 to 2021). A progressive, neurodegenerative disease characterized by loss of function and death of nerve cells in several areas of the brain leading to loss of cognitive function such as memory and language. "Despite that, targeted lipidomics analysis revealed increased levels of DAG in the plasma of Alzheimer’s disease patients, a clinical condition with indirect, however strong, pathophysiological connections with the G6PD activity." (PMID 29459896, 2018). "In Alzheimer’s disease, glucose-6-phosphate dehydrogenase (G6PD) and 6-PGD both increase in the cortex, suggesting that altered glucose metabolism is associated to the development of neurodegenerative disorders." (PMID 28746408, 2017). "G6PD plays an important role in compensating oxidative stress produced in Alzheimer’s disease." (PMID 30220890, 2018).
autoimmune disease (5 papers, 2018 to 2026). A disorder resulting from loss of function or tissue destruction of an organ or multiple organs, arising from humoral or cellular immune responses of the individual to their own tissue constituents. "Significantly increased rates were observed for autoimmune disorders, infectious diseases, and allergic conditions in G6PD-deficient individuals compared to the control group." (PMID 37753082, 2023). "The most striking finding of our study are the much-elevated rates of autoimmune diseases and chronic inflammatory conditions in G6PD deficient individuals." (PMID 37753082, 2023). "Compared to the group of asymptomatic or pauci-symptomatic patients, hospitalized patients also had a higher frequency of autoimmune diseases and glucose-6-phosphate-dehydrogenase (G6PDH) deficiency." (PMID 33343579, 2020). "Autoimmune diseases in G6PD deficient patients may be triggered by activation of TGF-β/NADPH oxidases/ROS signaling, the expression of ICAM-1 and VCAM-1, and the adhesion of leukocytes to the endothelial cells with endothelial to mesenchymal transition." (PMID 37753082, 2023). "Beyond infection, G6PD may also play a role in the immunopathology of autoimmune disease." (PMID 38938571, 2024).
cardiac hypertrophy (5 papers, 2018 to 2022). "We next sought to investigate if NaHS could modulate cardiac hypertrophy induced by β-AR stimulation and if G6PD was causally involved in such effects in our animal model." (PMID 29531803, 2018). "Our results, taken together, thus yielded strong evidence for regulation of a specific cardiac metabolic circuitry (involving G6PD as a key node) by H2S and its functional role in suppression of pathological β-AR stimulation—progressively culminating into cardiac hypertrophy." (PMID 29531803, 2018). "Next, we determined whether G6PD contributes to increase RV pressure and hypertrophy." (PMID 36372233, 2022). "Previous studies have found that the activity of the key enzyme in this pathway, glucose-6-phosphate dehydrogenase (G6PD), is increased when cardiac hypertrophy is present." (PMID 33287440, 2020). "Glucose-6-phosphate dehydrogenase (G6PD) is the rate-limiting enzyme that produce NADPH, and H2S may inhibit cardiac hypertrophy induced by adrenergic overstimulation by enhancing G6PD activity." (PMID 30298008, 2018). "For the same, we utilized 6-AN (specific G6PD inhibitor) in the animal model and studied the effect of H2S augmentation in conferring protection against β-AR stimulation (ISO) induced cardiac hypertrophy, with or without this inhibitor." (PMID 29531803, 2018).
chronic granulomatous disease (5 papers, 2011 to 2024). Chronic granulomatous disease (CGD) is a rare primary immunodeficiency, mainly affecting phagocytes, which is characterized by an increased susceptibility to severe and recurrent bacterial and fungal infections, along with the development of granulomas. "A null mutation of G6PD causes chronic granulomatous disease (CGD)-like syndromes and is incompatible with life in hemizygous males." (PMID 29180997, 2017). "G6PD is a key enzyme that shifts glucose metabolism toward PPP, and patients with G6PD deficiency exhibit such as deficient bacterial killing and chronic granulomatous disease due to dysregulated metabolic activity of neutrophils." (PMID 32121028, 2020).
congenital hypothyroidism (5 papers, 2018 to 2025). A thyroid hormone deficiency present from birth. "In the context of G6PD screening, the most common approach has been to include G6PD screening within other screening programs that are typically congenital hypothyroidism screening." (PMID 31709308, 2018).
deficiency anemia (5 papers, 2008 to 2025). "The results were consistent with glucose-6-phosphate dehydrogenase (G-6-PD)-deficiency anemia." (PMID 34620171, 2021).
lactic acidosis (5 papers, 2013 to 2024). Metabolic acidosis characterized by the accumulation of lactate in the body. "The literature on the association between ASD and respiratory chain abnormalities is growing, including complex III/IV deficiency and MELAS (mitochondrial encephalopathy, lactic acidosis, and stroke-like episodes) syndrome, as well as glucose-6-phosphate dehydrogenase deficiency." (PMID 33193781, 2020). "Collectively, these results suggest that G6PD is subject to dynamic phosphorylation at two tyrosine residues (Y249 and Y322) under lactic acidosis." (PMID 37491277, 2023). "To verify the inhibitory effects of NBDHEX on lactic acid signaling, we found that NBDHEX maintained the interaction of the tri-complex and the phosphorylation of G6PD even under lactic acidosis." (PMID 37491277, 2023). "Analysis of the microarray data for all the KEGG-listed PPP genes indicated that lactic acidosis induced the expression of G6PD, TKT and triose phosphate isomerase (TPI)." (PMID 24359630, 2013). "Lactic acidosis and acidosis respectively increase the expression and activity of glucose-6-phosphate dehydrogenase (G6PD), the first enzyme of the PPP, and lactic acidosis makes G6PD activity necessary to NADPH/NADP+ ratio maintenance and cell survival in glucose sufficiency." (PMID 36900208, 2023). "We also checked the S-glutathionylation of G6PD and SRC under lactic acidosis." (PMID 37491277, 2023).
liver disease (5 papers, 2020 to 2026). "Additionally, endogenous antioxidant enzymes, such as superoxide dismutase (SOD), glutathione peroxidase (GPx), glutathione reductase (GR), and glucose-6-phosphate dehydrogenase (G6PD), play a key role in modulating liver disease." (PMID 39596079, 2024).
malnutrition (5 papers, 2013 to 2024). Inadequate nutrition resulting from poor diet, malabsorption, or abnormal nutrient distribution. "In leukocytes, G6PD activity exhibits diurnal variation, is reduced in states of malnutrition, and is upregulated during bacterial infection." (PMID 38938571, 2024).
migraine (5 papers, 2018 to 2024). "We detected three energy metabolism-related enzymes (PKM, G6PD, and HK1) among the DEPs in the healthy controls and patients with migraine." (PMID 36248663, 2022).
psoriasis (5 papers, 2018 to 2024). An autoimmune condition characterized by red, well-delineated plaques with silvery scales that are usually on the extensor surfaces and scalp. "We also observed higher rates of inflammatory bowel disease (OR=1.34, P=.05) and psoriasis (OR=1.19, P=.02) among G6PD deficient patients." (PMID 37753082, 2023). "Meanwhile, 0.3% of participants either had glucose-6-phosphate-dehydrogenase deficiency (G6PD) or psoriasis." (PMID 36560566, 2022). "In atopic dermatitis and psoriasis, a G6PD signal was observed at sites of inflammatory cell infiltration." (PMID 38038136, 2023).
steatosis (5 papers, 2015 to 2024). Increased lipid within the cytoplasm of cells. "However, among the various steatosis-related parameters, CO supplementation only showed a slight improvement in G6PD compared to HFD." (PMID 35055664, 2022).
systemic lupus erythematosus (5 papers, 2014 to 2026). An autoimmune multi-organ disease typically associated with vasculopathy and autoantibody production. "Lupus with G6PD was found only in one article reporting 88 patients, and sporadic reports mentioned a scarce coexistence possibility of SLE with Castleman’s disease." (PMID 33143705, 2020).
X-linked hereditary disorder (5 papers, 2015 to 2024). "The most prevalent genes were GJB2 for autosomal recessive disorders and G6PD for X-linked diseases." (PMID 36072675, 2022).
aplastic anemia (4 papers, 2012 to 2024). Anemia resulting from bone marrow failure (aplastic or hypoplastic bone marrow). "In the our previous study, we also investigated the expression of polymorphisms at G6PD and IDS genes at the RNA level using nonradioactive RT-PCR method in 26 aplastic anemia patients and 35 normal females showed 3/35 (9%) clonallity pattern in normal controls." (PMID 23150832, 2012).
Autoimmunity (4 papers, 2015 to 2024). The occurrence of an immune reaction against the organism's own cells or tissues. "Could G6PD play a role in response to vaccination or in predispositions to autoimmunity?" (PMID 38938571, 2024).
Cerebral ischemia (4 papers, 2021 to 2026). Restriction of arterial blood supply to the brain associated with insufficient oxygenation to support the metabolic requirements of the tissue. "Furthermore, a recent study suggested that G6PD deficiency leads to poor prognosis and relatively high death rate in patients with cerebral ischemia." (PMID 36814490, 2023). "During the acute phase of cerebral ischemia-reperfusion, glucose 6-phosphate dehydrogenase (G6PD), a key enzyme in the PPP pathway, can be activated by ataxia telangiectasia mutated (ATM) kinase." (PMID 39911922, 2025). "Also, the expression of G6PD, the initial and rate-limiting PPP enzyme, and induction of the PPP promoted neuroprotection in brain ischemia." (PMID 41550715, 2026). "We previously reported that heat shock protein 27 (HSP27) phosphorylation plays an important role in the activation of glucose-6-phosphate dehydrogenase (G6PD), resulting in the upregulation of the pentose phosphate pathway and antioxidant effects against cerebral ischemia–reperfusion injury." (PMID 33557752, 2021).
Encephalopathy (4 papers, 2022 to 2025). Encephalopathy is a term that means brain disease, damage, or malfunction. "Multiple reports have demonstrated that G6PD-deficient infants have a significantly higher predisposition to neonatal jaundice and are more susceptible to acute bilirubin encephalopathy." (PMID 37492600, 2023). "Of the neonates with acute bilirubin encephalopathy, 37.5% (3 in 8) were G6PD-deficient." (PMID 37492600, 2023). "Moreover, one G6PD-deficient infant developed acute bilirubin encephalopathy with compound heterozygous mutations of c.392G > T and c.1388G > A." (PMID 37492600, 2023). "The data demonstrated that a significant proportion (82.8%) of patients with encephalopathy exhibited G6PD dysfunction." (PMID 39011425, 2024). "The table above shows that 82.8% of patients with encephalopathy had G6PD dysfunction." (PMID 39011425, 2024).